EIF4E (eukaryotic translation initiation factor 4E)
Diseases named in the same sentence as EIF4E in open-access papers (continued):
Sharing a sentence is not in itself a finding about the gene and the disease.
cancer (continued). "It has been reported that EIF4E protein contributes to malignant transformation and progression by enhancing translation of cancer-related mRNAs in eukaryotic cells." (PMID 34659334, 2021). "4E-BP1 is also overexpressed in a multitude of cancer types, inhibiting the pro-oncogene eIF4E, but also favoring tumorigenesis, especially in the context of cellular stress." (PMID 34519641, 2021). "Cancer biology studies have indicated a possible convergence of both pathways that positively regulates eIF4E-sensitive cap-dependent mRNA translation." (PMID 34172827, 2021). "The translation of tumor-associated proteins is controlled by mitogen-activated translational factor eIF4E, the expression of which is elevated in cancer cells." (PMID 33916175, 2021). "One of the main features of cancer onset and progression is the malfunctioning of the translation machinery, resulting in an increase of protein synthesis due to eIF4E dysregulation." (PMID 34541613, 2021). "Like eIF4E and eIF4G, eIF4A overexpression has been documented in a variety of cancer types, including breast, lung, and cervical carcinoma." (PMID 34639005, 2021). "Although, as suggested by the authors, these results support the study of this eIF4E ASO in combined with other cancer treatment modalities, the effect of a combination with radiotherapy (to our knowledge) have not been reported." (PMID 34639005, 2021). "According to previous research reports, among the four significantly regulated downstream genes found in this experiment, CDH1 was considered to be an anti-oncogene, and ETS1, RAF1 and EIF4E play roles in promoting cancer." (PMID 34671562, 2021). "In contrast, eIF4E is often overexpressed in cancer cells, thereby promoting cell growth and survival." (PMID 33833335, 2021). "eIF4E is a crucial translation initiation factor, also involved in the onset of a number of cancer types (see discussion below)." (PMID 35582305, 2021). "It has been revealed that the global translation rate of eukaryotic gene expression is mainly limited in the initiation step mediated by eIF4E and that eIF4E is important for initiating the translation of pro‐oncogenic mRNA in cancers (2015)." (PMID 32460412, 2021). "For example, Eukaryotic Translation Initiation Factor 4E (eIF4E), which has increased levels in cancer, promotes tumorigenesis through mRNA-mediated cellular functions that include, for example, proliferation or angiogenesis." (PMID 33923168, 2021). "Targeting eIF4E as a cancer treatment strategy has primarily focused on antisense oligonucleotides (ASO)." (PMID 34639005, 2021). "Eukaryotic translation initiation factor 4E (EIF4E) is a target of the mTOR pathway, which can affect numerous cancer phenotypes." (PMID 34425750, 2021). "Many cancer cells exhibit a reduction of 4E-BP expression or increase in eIF4E expression, enabling cap-dependent translation even following mTORC1 inhibition." (PMID 33318657, 2021). "The expression level of mRNA cap‐binding protein eIF‐4E is elevated in multitudinous carcinomas compared with normal tissues and benign lesions." (PMID 34120414, 2021). "Several compelling lines of evidence from animal studies indicate that the elevated levels of eIF4E phosphorylation are closely related to the development and progression of cancer." (PMID 33148274, 2020). "The most studied translation factors that function as oncogenes during tumor formation, growth, invasion and metastasis in various cancers include eIF4E and its repressors 4E-BPs, as well as eIF2α, eIF3, eIF2α, eIF5A." (PMID 32973493, 2020). "These and other studies have identified key targets of eIF4E that are essential for cancer cell proliferation, survival, and migration, such as cyclin D1 and D3, c-Myc, MDM2, VEGF, Survivin, and Bcl-2." (PMID 32731503, 2020). "Reductions in p-eIF4E level with a MNK1/2 inhibitor reduced the expression of PD-L1 in a MYC/KRAS model of cancer." (PMID 32759815, 2020).
cancer (continued). "The Akt (protein kinase B)/mammalian target of rapamycin (mTOR) pathway, which is dysregulated in various cancers, controls the assembly of eukaryotic translation initiation factor 4F (eIF4E) complex." (PMID 32023262, 2020). "It has been suggested that post-translational modifications play an important role in the control of EIF4E activity in cancer." (PMID 33266490, 2020). "Ouabain, perillyl alcohol, and mTOR inhibitors (e.g., rapamycin, Torin1, and AZD8055) also interrupt the interactions of eIF4E and eIF4G in various cancer cells." (PMID 32967226, 2020). "Together, these studies expand our current knowledge on IRF8 and eIF4E-mediated regulation of IRF8 in the host defense against cancer." (PMID 32731503, 2020). "MKNK1 is target of both RAS/RAF/ERK and MKK/p38 MAPK pathways and regulates the activation of eIF4E (eukaryotic translation initiation factor 4E), strongly upregulated in cancer patients and correlated with disease progression." (PMID 32316313, 2020). "EIF4E is modestly altered in cancers at the DNA level, with a profile resembling the tumor suppressor RB1 more than the MYC oncogene." (PMID 33266490, 2020). "It has been shown eIF4E overexpression in a variety of cancers including breast, bladder, colon, head and neck, kidney, lung, skin, ovarian and prostate compared to healthy tissues and its relationship with disease progression." (PMID 32340135, 2020). "The inhibition of eIF4E has been shown to have therapeutic potential for the treatment of several types of cancer." (PMID 33148274, 2020). "eIF4E is overexpressed in cancer and exerts oncogenic potential by regulating mRNAs related to proliferation (c-Myc, CDK2, and Cyclin D1), metastasis (MMP9 and heparanase), loss of apoptosis (Mcl-1, Bcl-2, and survivin), and angiogenesis (VEGF and FGF2)." (PMID 32967226, 2020). "EIF4E is frequently overexpressed in various types of cancers, and its overall phosphorylation is significantly higher in tumor tissue compared to paired normal tissues, thus supporting the critical role of EIF4E in cancer." (PMID 32483460, 2020). "Further, studies performed in human cancer cells have shown that MNK-dependent eIF4E phosphorylation is regulated by PI3K signaling." (PMID 31921404, 2020). "Both FGFR3 and eIF4E have previously been shown to be overexpressed in several types of cancers, including CRC, and they have both also been found to promote tumor growth." (PMID 32731506, 2020). "Overexpression of eIF4E is the main mechanism for eIF4E activation and has been discovered in many cancer tissues." (PMID 33489719, 2020). "The best-studied translational regulator involved in cancer is the eukaryotic translation initiation factor 4E (eIF4E), which is regulated via phosphorylation of serine 209 by the mitogen-activated protein kinase integrating kinases 1/2 (MNK1/2)." (PMID 33101283, 2020). "In BC and other cancers, eIF4E is frequently over-expressed in the very early stage, especially in the pre-invasive stage (such as carcinoma in situ) and associated with the malignant progression of a high tumor grade." (PMID 32708122, 2020). "eIF4E activity is increased in cancers not only from the increased protein synthesis demands but also because it selectively enhances translation of a subset of mRNAs responsible for proliferation and survival." (PMID 33266490, 2020). "Another nucleoside analog, ribavirin, was also reported to be an eIF4E-cap inhibitor and an anti-eIF4E cancer therapeutic." (PMID 33148274, 2020). "eIF4E is highly elevated in a broad array of human cancers where this typically correlates with poor prognosis." (PMID 33375634, 2020). "Some studies have shown that eIF4E was correlated with the occurrence and development of human cancers, and the inhibition of eIF4E expression acted as a potential therapeutic target." (PMID 33489719, 2020). "The results showed that B591 increased eIF4E [nuc:cyto] ratios in all the five cancer cells in a dose-dependent manner." (PMID 30635656, 2019).
cancer (continued). "eIF4E highly expresses in a variety of human malignancies and is relevant to cancer development and progression." (PMID 31703598, 2019). "Suppression of 4EBP1 protein leading to reduction in eIF4E enhanced the radiosensitivity of several human cancer cells." (PMID 31024849, 2019). "As a consequence, eIF4E deregulation by MNKs promotes cancer cell proliferation, malignant transformation and metastasis." (PMID 31795417, 2019). "Therapeutic targets of mRNA translation such as eIF4E, 4EBP, and eIF2, for cancer treatment or stem cell fate regulation are reviewed." (PMID 31671902, 2019). "Increasing evidence suggests that high expression of eIF4E is related with oncogenic transformation in cell culture, tumor initiation and progression in mouse models, and poor prognosis in various human cancers." (PMID 31695627, 2019). "Taken together, these various lines of evidences point to a notion that the mechanisms whereby eIF4E is phosphorylated in cancer cells are complicated and require further investigations." (PMID 30804329, 2019). "One of the candidate signaling molecules that is involved in cancer progression is eIF4E, the cap-binding component of eIF4F, at which the growth and proliferation signals converge, making it an important factor that controls cell normality." (PMID 31671902, 2019). "The PI3K-AKT-mTOR pathway is one of the most commonly altered pathways in cancer and has a role in promoting translation initiation through mTORC1-dependent hyper-activation of EIF4E." (PMID 31496918, 2019). "Although it is unclear why cells produce more eIF4E than is needed, it appears that cancer cells use this to benefit their survival." (PMID 31671902, 2019). "In PCa cells, miR‐455‐3p inhibits cancer cell proliferation by targeting the transcription factor eIF4E." (PMID 30444038, 2019). "Hyperactivation of the mTOR pathway occurs in majority of the cancers, which results in increased eIF4E activity." (PMID 31586263, 2019). "In previous studies blocking eIF4E phosphorylation was shown to suppress mRNA translation of oncogenic genes, leading to inhibition of cancer cells proliferation." (PMID 31903169, 2019). "eIF4E is frequently overexpressed in cancers—leukemic, breast, ovarian, esophageal, colon and cervical." (PMID 31825993, 2019). "In various cancer cells originating from the breast, colon, prostate, lung, skin, and bladder, enhanced eIF4E is commonly observed." (PMID 31671902, 2019). "Elevated levels of phosphorylated eIF4E are found in human cancer tissues obtained from patients with lung, head, colorectal, and gastric cancers and primary pancreatic ductal adenocarcinoma." (PMID 29568373, 2018). "Mechanistically our data show that asTORi treatment initially represses global mRNA translation, but HSV1-dICP0 protein expression persists in cancer cells and cells with dysregulated eIF4E/4E-BP ratio." (PMID 30138450, 2018). "The study of eukaryotic initiation factor 4E (eIF4E) is a key focus in cancer research due to its role in controlling the translation of tumour-associated proteins, that drive an aggressive migratory phenotype." (PMID 29581834, 2018). "Since eIF4E is overexpressed in many human cancers (by ∼3- to 10-fold), LY2275796 has been tested as an anti-cancer treatment." (PMID 30459806, 2018). "The hyperactivation of two major signalling pathways, PI3K/AKT/mTOR and Ras/MAPK/MNK, occurs in the majority of the cancers and eIF4E acts as a convergence point for both signalling pathways to promote tumorigenesis." (PMID 29568373, 2018). "In contrast, viral protein synthesis persists in cancer cells and cells transduced to either increase eIF4E levels or deplete 4E-BP1/2, ultimately resulting in enhanced viral replication and spread." (PMID 30138450, 2018). "Targeting the mTORC1/4E-BPs/eIF4E axis is a promising strategy in cancer therapies and for preventing resistance to treatment." (PMID 30138450, 2018).
cancer (continued). "In cancer, mRNA translation is frequently dysregulated because of increased eIF4E protein levels and/or elevated phosphorylation of 4E-BPs due to a hyperactivated mTORC1 pathway." (PMID 30138450, 2018). "Silencing eIF4E led to a strong repression of HSV1-dICP0 infection in cancer cells treated with asTORi, while silencing 4E-BP1 or 4E-BP2 had a reverse effect." (PMID 30138450, 2018). "eIF4E phosphorylation was previously suggested to control cancer metastasis, by controlling ECM function and in particular the translation of MMPs, such as MMP-9." (PMID 29367404, 2018). "Several studies identified phospho-eIF4E-sensitive mRNAs in cancer models; however, in brain, only a small subset was revealed." (PMID 29367404, 2018). "Leukemia cells express a high level of phosphorylated eIF4E; inhibiting phosphorylation of eIF4E represents a unique approach for the treatment of cancer development and progression." (PMID 30388805, 2018). "It has been shown that eIF4E overexpression in a variety of cancers including breast, head and neck, colon, prostate, kidney and lung is related to disease progression." (PMID 29568373, 2018). "The central role of eIF4E as a highly regulated component of the eIF4F complex and its overexpression in several cancers make eIF4E an attractive target for the development of therapeutic agents." (PMID 29799508, 2018). "On the other hand, overexpression of the oncogene HMD2 in cancer cells is regulated by eIF4E, so that the overexpression of eIF4E promotes the export of the HDM2 mRNA in a MAP kinase- and Mnk1-dependent manner." (PMID 29568373, 2018). "Activated mTOR contributes to OS cellular transformation and poor cancer prognosis via targeting the downstream effectors such as EIF4E." (PMID 29921292, 2018). "Protein eIF4E levels are rate limiting; phosphorylation of 4E-BPs during aberrant mTORC1 activation in cancer is a strong inducer of cap-dependent translation." (PMID 30096805, 2018). "eIF4E is an oncogene as it is overexpressed in many human cancers with poor prognosis and its overexpression results in the transformation of cells in vivo." (PMID 30096805, 2018). "Cancer cells can markedly amplify the protein levels of CCND1 by either over-expressing eIF4E or aberrantly activating mTORC1 (or both) and consequently are able to accelerate through the G1-S phase of the cell cycle." (PMID 29301334, 2018). "Phosphorylated eIF4E (p-eIF4E) is overexpressed in a broad spectrum of human cancers, including cancer of lung, gastric, prostate, colorectal, breast, and penile, when compared with matched adjacent normal tissues." (PMID 28878291, 2017). "In cancer, overexpression of HuR leads to eIF4E mRNA stabilization and consequently elevated eIF4E protein levels." (PMID 28798901, 2017). "eIF4E is one of the most thoroughly investigated translation factors involved in cancer biology, especially in CRC." (PMID 29254159, 2017). "At the same time, aberrant activation of eIF4E, as a mechanism of drug resistance, has been described in several cancers." (PMID 28417568, 2017). "In accord with this, miR-34c-3p expression is significantly decreased in NSCLC patient biopsies as well as cancer cell lines, which thus allows overexpressed EIF4E to promote lung carcinogenesis." (PMID 28903455, 2017). "It is evident that an increase in eIF4E activity is oncogenic due to the many ways this is achieved in cancer cells such as gene duplication, increased EIF4E transcription, and increased eIF4E availability due to constitutive mTORC1 activation." (PMID 29317983, 2017). "It is known that eIF-4E levels and cap-dependent translation are frequently elevated in malignancies of the prostate, lung, breast, as well as many other organs." (PMID 28054974, 2017). "Multiple lines of recent evidence have shown that inhibiting eIF-4E function in cancer cells lead to cell apoptosis." (PMID 28054974, 2017).
cancer (continued). "EIF4E activation is the rate‐limiting step in translation initiation and facilitates the metastasis of numerous types of cancer." (PMID 28661037, 2017). "It was reported that 4Ei-1 can reduce proliferation and repress colony formation of cancer cells by inhibiting eIF-4E function." (PMID 28054974, 2017). "Aberrant expression and activation of aurora kinase A (AURKA) and eukaryotic translation initiation factor 4E (eIF4E) are detected in several cancer types." (PMID 28417568, 2017). "Phosphorylation of eIF4E via Mnk1 increases its activity, and this event is common in various cancers to drive their progression." (PMID 29317983, 2017). "So far, therapeutic strategies targeting the translational machinery components in cancer focused on the eukaryotic translation initiation factor 4F complex and specifically the EIF4E subunit." (PMID 29050215, 2017). "Cancer cells displayed a shifted window of dual eIF4E and eIF4E2 usage (3–12% O2) suggesting that eIF4E2 is activated and eIF4E is sequestered at higher oxygen levels relative to primary cells." (PMID 29317983, 2017). "Abundant researches have demonstrated that overexpressed eIF4E was significantly correlated with tumor malignant characteristics, resistance to therapy, and regarded as the poor prognosis predicator for human cancers." (PMID 27588477, 2016). "Dual targeting of both Akt and mTOR, or directly inhibiting eIF4E activity has been proposed as treatments for cancer." (PMID 27050281, 2016). "Ablation of 4E-BP3 in cancer cells reveals that it plays an important role in controlling translation of eIF4E-target mRNAs and cell proliferation." (PMID 27319316, 2016). "This depicted the potential of 3-AWA to inhibit eIF4E mediated cancer cell proliferation and metastasis." (PMID 26728896, 2016). "Similar GNBs were abundantly detected in all 48 different cancer cell lines by p-eIF4E antibody, but not by t-eIF4E antibody." (PMID 26678034, 2016). "The high expression of p-eIF4E has been verified in a variety of human cancers and predicts poor prognosis." (PMID 27050281, 2016). "The PI3K/Akt pathway has been caught much of the attention for its increased pathway activation in resistant cancers, which also promotes abnormal expression of eIF4E." (PMID 27588477, 2016). "Consistently, highly phosphorylated eIF4E (p-eIF4E) was frequently observed in a variety of human cancers." (PMID 26678034, 2016). "To further evaluate the role of eIF4E in human ESCC, we next examined the association between eIF4E and several clinical parameters, including age, gender, TNM, and cancer grade in 90 ESCC patients." (PMID 27588477, 2016). "eIF4E is overexpressed in numerous human tumours, and it contributes to transformation, tumourigenesis, and progression of cancers." (PMID 27592390, 2016). "In contrast, studies have shown a positive correlation between increased eIF4E phosphorylation and cancer cell proliferation as well as tumorigenesis." (PMID 26678034, 2016). "Since mTOR inhibitor- induced eIF4E phosphorylation is PI3K and Mnk dependent, one strategy to improve an mTOR inhibitor’s efficacy against cancer is to prevent eIF4E phosphorylation by combining an mTOR inhibitor with a PI3K inhibitor or a Mnk inhibitor." (PMID 26728896, 2016). "High levels of the cap-binding protein eIF4E promote cell growth and proliferation in cancers including ovarian, esophageal, breast, thyroid, and prostate cancers, as well as leukemias." (PMID 26357652, 2015). "Cancer cells treated with the Mnk1/2 inhibitor CGP57380 to prevent eIF4E phosphorylation and mouse embryonic fibroblasts derived from Mnk1/2 knockout mice were also more sensitive to arsenite and cisplatin treatment." (PMID 25923732, 2015). "eIF4E is an oncogene with prognostic value in various human cancers, including head and neck squamous cell carcinoma and breast cancer." (PMID 25923732, 2015).